AR (androgen receptor)
Diseases named in the same sentence as AR in open-access papers (continued):
Sharing a sentence is not in itself a finding about the gene and the disease.
cancer (continued). "The detected overexpression in cancerous tissues was 682-fold for AMACR mRNA and 11.5-fold for AR mRNA compared to prostates without any evidence of cancer." (PMID 26928323, 2016). "From these samples, we identify established driver aberrations in a cancer-related gene in nearly all cases (97.7%), including driver gene fusions (TMPRSS2:ERG), driver focal deletions (PTEN, RYBP and SHQ1) and driver amplifications (AR and MYC)." (PMID 27328849, 2016). "This is the first time that stromal AR changes have been shown to be specific to the immediate cancer microenvironment and not due to differences between patients, and are related to adjacent malignant but not benign regions of the same prostate." (PMID 25965833, 2015). "AR, MMP-2 and MMP-9 may be predictive markers for HCC and could be regarded as candidates for indicating the cancer stage." (PMID 25667651, 2015). "In muscle-invasive tumors, p-ELK1 positivity strongly correlated with cancer-specific survival (HR = 2.693, P = 0.021), whereas positivity of AR (HR = 2.280, P = 0.042), but not that of p-ELK1, was identified as a strong predictor for disease progression." (PMID 26342199, 2015). "It is also important to note that resistance and proliferation abilities of PC cells due to activated pathways by non-genotropic activities of AR will be eliminated resulting in an enhanced anti-cancer activity." (PMID 26196320, 2015). "We chose ERK, TGFB1, TGFB2, SIRT1, IL-6, PI3K, and WHSC1 (which were controlled by several genes) and three other genes AR, BCL-XL, and CCND1 that could mark the deterioration of the cancer, for testing." (PMID 26603105, 2015). "VT-464 demonstrated anti-cancer activity in preclinical models of advanced CRPC, significantly lowering tumoural androgen levels in castrate mice, and enforcing greater suppression of the AR signalling axis compared to abiraterone." (PMID 25896606, 2015). "In contrast to AR pathway inhibitors, catalytic Topo II inhibitors target not only AR-mediated transcription initiation but also suppress cancer cell mitosis." (PMID 26009876, 2015). "The other group uses a mechanism to bypass AR signaling pathways, which allows cancer cells to survive in the absence of androgen-dependent or -independent AR activation." (PMID 25537508, 2015). "The initial combined analysis of carcinoma cells and fibroblasts did not identify AR targets as significantly altered." (PMID 25575823, 2015). "Interestingly, genes that have been previously found to be overexpressed in other cancers such as hepatocyte growth factor (HGF), laminin alpha 4 (LAMA4) and androgen receptor (AR) were also found to be more highly expressed in MEi cells compared to BM-MSCs." (PMID 25229469, 2014). "In general, it is thought that the role of AR in castration resistant cancer cells is not to direct the androgen-dependent gene expression program without androgen, but rather to execute a distinct program resulting in androgen-independent growth." (PMID 25277175, 2014). "The aim of this study was to identify a new factor that controls AR signaling indirectly in HRPC patients, and to examine whether GAK could be targeted for the therapy of not only HRPC but also other cancers with enhanced GAK expression." (PMID 24971999, 2014). "In triple negative cancers the percentage of androgen receptor positive cases was lower (24.8% vs 81.6% of non-triple negative cases), especially in African American women (16.7% vs 25.5% of cancers of white women)." (PMID 24505496, 2014). "Recently, a mouse cancer model lacking the AR only in the prostatic epithelium and/or stroma has been generated (ARKO-TRAMP)." (PMID 24744780, 2014). "If ER and AR are functionally important for WDLS/DDLS cell proliferation or viability, as is observed in other cancer types such as breast and prostate, anti-hormone therapies may prevent LS progression." (PMID 25349530, 2014).
cancer (continued). "When ER negative cancer was divided into groups according to AR and HER-2 status, these groups exhibited a noticeable difference in age at diagnosis and Ki-67 expression levels." (PMID 25140630, 2014). "AR mRNA was significantly down-regulated in primary and metastatic TNBC samples in comparison to normal breast tissue (both p<0.001), and significant up-regulation was observed in metastatic samples in comparison to primary cancers (p = 0.02)." (PMID 24505496, 2014). "These putative androgen receptor negative cancer stem cells are likely to be resistant to most androgen-based therapies, contributing to the evolution of castration-resistant disease." (PMID 25277175, 2014). "HER2 positivity was more frequent in molecular apocrine carcinomas (42.9% as opposed to 17.1% in HR + (AR+/-) and 15.8% in HR-/AR-, p < 0.0001)." (PMID 25070172, 2014). "51.5% of AR positive tumors were also positive for GCDFP-15, whereas only 24% of AR negative carcinomas showed GCDFP-15 staining (p < 0.0001)." (PMID 25070172, 2014). "If the expression of the AR can interfere with the activity of tamoxifen, the use of tamoxifen should be confined to AR-negative cancers." (PMID 24403250, 2013). "Because our results in TRAMP mice showed that BA treatment did not reduce AR protein levels in non-cancerous prostate, we sought to determine the effect of BA on non-cancer cells by utilizing BJ human foreskin fibroblast cells." (PMID 23424652, 2013). "The results from preclinical experiments with AR targeting therapeutics have clearly demonstrated that “castrate-resistant” cancers are not independent of AR transcriptional signaling." (PMID 23781155, 2013). "The findings reported here on the effect of AR/Src complex inhibition on cell invasiveness clearly suggest new roles to be played by steroid receptors in cancers derived from non-hormone dependent tissues." (PMID 24130806, 2013). "Both stem cells and cancer stem cells described by these signatures from primary human prostates have typically lacked AR expression." (PMID 23145034, 2012). "YY1 expression is elevated in PIN and intermediate stage disease, and its interaction with AR may result in increased PSCA expression in PIN and well-differentiated cancers." (PMID 22536409, 2012). "In addition, recent findings demonstrated a cooperation between TMPRSS2/ERG fusion and deregulated activity of cancer-related pathways, such as PTEN, PI3-Kinase, and AKT or AR." (PMID 21747944, 2011). "Since cytosolic or no AR protein was observed in some of the cancer cells, it appeared that androgens were not necessarily required for survival of these cells or otherwise they should had been programmed into cell death." (PMID 21241512, 2011). "Compared to the luminal-like types, the non-luminal-like cancer cells show less features of secretory differentiation such as decreased expression of KLK3 and AR, and expression of markers associated with more primitive cell types." (PMID 21605402, 2011). "Cancer chemopreventive response to PEITC is characterized by its ability to inhibit multiple oncogenic signaling pathways, including nuclear factor-κB, Akt, and androgen receptor." (PMID 22039516, 2011). "These androgen-independent (AI) tumors paradoxically depend on the AR, suggesting that AR-mediated signaling is required for the growth of cancer cells, even when absent or present only in low concentrations." (PMID 20504375, 2010). "In a minority of cancers, DNA-based alterations to the AR allow it to bind to non-canonical ligands such as estrogen and cortisone, and in some cases, clinical AR antagonists such as flutamide." (PMID 20406442, 2010). "In our study, two of three PSA-positive carcinomas were positive for AR, ER, and PR, and the hormone receptor-negative case demonstrated focal weak AR expression that did not meet our 10% threshold for AR positivity." (PMID 20863373, 2010).
cancer (continued). "Multiple PCa cell lines were examined: PC3 is metastatic hormone refractory androgen receptor (AR)-negative, LNCaP is metastatic AR-positive, while 1532NPTX and 1523CPTX are AR-negative paired primary normal and cancer cells, respectively, isolated from the same patient." (PMID 41597241, 2026). "Notably, the interaction term (YAP × AR) further amplified this risk by an additional 1.80-fold (95% CI 1.20–2.70, P = .004), indicating that YAP and AR do not act independently but rather exacerbate malignant tumor progression through a synergistic mechanism." (PMID 41517748, 2026). "Unlike AR, ERs and PR showed positive correlations with immune infiltrates in most cancer types." (PMID 41486951, 2026). "Positively co-expressed genes showed a strong positive correlation with epithelial to mesenchymal transition in 23 different cancers, while also exhibiting a negative correlation with DNA damage (n = 17), cell cycle pathways (n = 10), and the AR pathway (n = 14)." (PMID 40233044, 2025). "Additionally, QW07 was more effective in AR-positive cancer cell lines than in AR-negative or healthy cells, as evidenced by lower IC50 values, suggesting selective cytotoxicity and a potentially improved therapeutic window." (PMID 41374958, 2025). "Furthermore, the AR pathway promotes the transcription of genes involved in epithelial-mesenchymal transition (EMT), increasing the invasiveness and metastatic potential of cancer cells." (PMID 39757310, 2025). "In primary tumors, cytoplasmic or membranous MUC1 did not significantly differ between cases with (n = 16) and without (n = 101) distant metastases, whether analyzing all carcinoma cells or putative AR structures (p = 0.168–0.902)." (PMID 41332218, 2025). "Androgens can activate both a rapid and late response pathway in the AR signalling cascade, with the former dependent on the Raf-1-MEK pathway, resulting in the upregulation of pro-survival, proliferation, and metastatic gene expression, pathways that contribute to key hallmarks of cancer." (PMID 39858418, 2024). "Nevertheless, the lineage plasticity of prostate carcinomas from adenocarcinomas to neuroendocrine androgen receptor-negative cancers represents a major change in cancers, worsening prognosis, and may be due to epigenetic differences." (PMID 38660133, 2024). "Several recent studies have indicated that androgens may function via mAR to increase AR-negative cancer progression." (PMID 36800968, 2023). "Importantly, although ecDNA is known to occur with higher frequency in PDX models than clinical specimens across multiple cancers, we demonstrated this AR ecDNA FISH staining pattern in all 4 clinical CRPC tumors harboring multiply-rearranged AR gene structures." (PMID 37636316, 2023). "While the most widely accepted mode of action of enzalutamide is targeting AR activity, there is evidence that this drug also triggers apoptosis and attenuates the expression of anti-apoptotic proteins and heat shock proteins such as HSP27 in PCa cells and other cancer cell types." (PMID 37626856, 2023). "Moreover, ERα and AR proteins increased, whereas ERβ and PGR diminished markedly in neoplastic relative to non-neoplastic colonic tissues, and the dysregulations were maximal in late-stage cancers in both genders." (PMID 37206439, 2023). "In addition to its antiproliferative activity in the low micromolar range against several cancer cell lines, including androgen-independent and androgen-dependent PC cell lines, RM-581 has been shown to be highly active (IC50~0.5 μM) on the AR+ metastatic LAPC-4 cell line used in the present study." (PMID 37296995, 2023). "Such a proxy might be interesting as AR-amplified cancers have been shown to respond better to second-line maximal androgen blockade compared to tumors without AR amplification." (PMID 36983083, 2023).
cancer (continued). "The response in AR-sensitive LNCaP cell lines to 27HC compared to AR-negative DU145 cells may suggest that 27HC has a more pronounced effect on DNA damage/repair pathway gene expression in androgen sensitive cancers." (PMID 38188290, 2023). "To further examine whether UA inhibits PCa cell growth through disrupting AR signaling, we compared the anti-cancer effects of UA and digoxin in AR-positive and -negative PCa cells." (PMID 37180705, 2023). "Therefore, potentially in high passage cancer cells PI3K/Akt and AR signalling may synergistically to increase glucose metabolism." (PMID 35326402, 2022). "Additionally, we established both AR-FL and AR-V7 action can promote cell migration and invasion through EMT signaling in agreement with multiple reports showing AR signaling plays a role in cancer metastasis." (PMID 36430245, 2022). "In contrast, mir-449a/b and mir-135a-1/2 were downregulated in AR-negative cancers." (PMID 36550153, 2022). "Basal cells, which express very little or no AR, are in direct contact with luminal cells via gap junctions and form a barrier between the luminal cells and the stroma and, like luminal cells, basal cells can give rise to cancers." (PMID 36263323, 2022). "Furthermore, the percentage of patients with mCRPC with a substantial fractions of cancer cells lacking AR has more than tripled over the last decade, due to therapy-induced lineage plasticity." (PMID 36561929, 2022). "Furthermore, the sensitivity of cancer cells to immune-mediated lysis was independent of detectable AR expression, both in enzalutamide and abiraterone treatment." (PMID 33915941, 2021). "Interestingly, Ili-A suppressed the binding of EZH2 to promoter regions in AR/serine/threonine polo-like kinase-1/aurora kinase A. Moreover, Ili-A could enhance the anticancer activity of enzalutamide in CRPC cancer models." (PMID 34776951, 2021). "However, it has also been shown that the AR-stimulated transcriptome in cancer cells is quite distinct from that in non-malignant cells, which complicates any study of unfractionated human tissue where normal cells frequently coexist." (PMID 33477370, 2021). "Although, CRPC is frequently associated with the loss of AR expression, recent studies describe that anti-androgen resistance and PCa progression can be acquired via an AR indifferent state, where cancer cells do not depend on AR signaling regardless of persistent AR expression." (PMID 33572476, 2021). "Despite this intricate biological complexity, the PCa field has predominantly focused on the AR in isolation for the derivation of activity-based gene signatures to predict whether individual cancers are AR-dependent or not." (PMID 33525365, 2021). "Rather, it is an example of an AR–/NE– double-negative (DN) PC (DNPC) heterogeneously composed of cells expressing both basal and luminal cell characteristics, suggestive that their cancer-initiating cell was an AR– progenitor cell whose malignant transformation did not require exposure to ARSis." (PMID 33724955, 2021). "The analyses of RNA-seq data of LNCaP/AR and LNCaP/AR-shp53/shRB revealed that ELOVL5 was upregulated in NE-like enzalutamide resistant LNCaP/AR-shp53/shRB cells compared to LNCaP/AR cells, which was further confirmed by RT-qPCR and the expression pattern in different cancer tissues." (PMID 34439125, 2021). "RING-type E3 ubiquitin transferase (RNF6) is known for its ubiquitination of various substrates, including the androgen receptor (AR), transducin-like enhancer of split 3 (TLE3) and the tyrosine phosphatase, SHP-1, in order to mediate the proliferation of various types of cancer cells." (PMID 34685511, 2021).
cancer (continued). "Similar levels of E-cadherin downregulation were also identified in persistent luminal cells within benign glands, which also expressed predominantly nuclear AR, confirming that the adaptive response that permits epithelial survival is not cancer cell–specific." (PMID 34322653, 2021). "Our results reveal how AR signaling can display different nonlinear emergent dynamics (oscillations, bistable) and therefore generate and maintain non-genetic heterogeneity in an isogenic cancer cell population." (PMID 33652914, 2021). "AR dependence on cofactors at sAREs may be the basis for differential modulation by dox that preserves expression of genes for survival but not cancer progression." (PMID 32198885, 2020). "In addition to regulating AR, GSEA and additional gene ontology analysis of genes differentially expressed following ERβ activation revealed an enrichment of genes involved in cancer-related processes, including apoptosis, response to hypoxia, KRAS signaling, and key metabolic pathways." (PMID 32413024, 2020). "Ongoing clinical trials with ASOs targeting Bcl-2 (NCT04072458), Grb2 (NCT04196257), and androgen receptor (AR; NCT03300505) as well as future mRNA and non-coding RNA targets for the treatment of various solid tumors will in time tell of the efficacy of ASOs for cancer treatment." (PMID 32373584, 2020). "Thus, GTPs, especially EGCG, suppressed cancer cell growth by modulating the acetylation of AR by HAT activity in androgen-dependent, but not in androgen-independent, PC cells." (PMID 30621039, 2019). "We developed PEG3AP1-3STA, a cancer-specific system that can image heterogeneous populations of PCa cells, including adenocarcinoma and neuroendocrine differentiated cells, with or without androgen receptor expression." (PMID 30626088, 2019). "Importantly, since GATA2 functions upstream of NR3C1 and other enzalutamide-induced cancer-promoting genes (e.g. SLC7A11 and LAMP3), targeting GATA2 maybe a better strategy for improving AR-targeted therapy by enzalutamide." (PMID 31501863, 2019). "However, a study among 590 women found that AR did not predict tamoxifen response in AR+/ER+ cancers, though it did suggest a benefit to tamoxifen treatment for AR+/ER− cancers." (PMID 30795773, 2019). "AR expression or activity may not reflect cancer cell dependency on the androgen pathway and therefore may not predict response to AR antagonists or AR modulators." (PMID 34926721, 2019). "Our previous results suggest that the PCa-specific ability of BA to decrease AR and other pro-survival proteins and increase cell death may be due to inhibition of multiple DUBs in cancer but not in non-cancer cells." (PMID 30177856, 2018). "Our data is supportive of the hypothesis that inhibiting the activity of multiple and selective DUBs with BA or WP decreases AR/AR-V7 variant expression and kills PCa and CRPC cells without harming non-cancer cells." (PMID 30177856, 2018). "These new evidences suggest that downregulation of AR may exert an oncogenic role in advanced CRPC, at least some subpopulations of CRPC; and restoration of AR expression and its signaling might be beneficial to some advanced patients with NEPC or mCRPC patients with cancer stem-like cell phenotype." (PMID 29555975, 2018). "And CD44 expression could be detected in AR knockdown cancer cells, but not in control group, indicated by western blot results." (PMID 29423076, 2018).